IDO2 (indoleamine 2,3-dioxygenase 2)
Diseases named in the same sentence as IDO2 in open-access papers (continued):
Sharing a sentence is not in itself a finding about the gene and the disease.
cancer (54 papers, 2014 to 2025). A tumor composed of atypical neoplastic, often pleomorphic cells that invade other tissues. "Only 6 cancers were associated with expression of IDO2, 5 of which were associated with expression of the 2 Trp transporters, IDO1 and TDO2, and 2 with FAMID." (PMID 36286592, 2022). "In effect, d-1-MT, under the name indoximod, is developed clinically as the IDO2 inhibitor for the treatment of several cancers with the general aim of reversing cancer-associated immunosuppression." (PMID 34201791, 2021). "This is because TDO expression has been implicated in cancer states, and IDO2 is inactive in some common polymorphisms." (PMID 29651242, 2018). "Additional studies encourage the notion that IDO2 may offer some pathogenic support to advanced cancer in certain settings, albeit less widely than IDO1." (PMID 25477879, 2014). "In contrast to cervical cancer, overexpression of IDO2 is found in most cancers (e.g., GC, colon cancer, and renal tumors)." (PMID 40332338, 2025). "Enzymes, such as indoleamine-2,3-dioxygenase 1 (IDO1), IDO2, or tryptophan-2,3-dioxygenase, catalyze this, thereby modulating immunity and fostering cancer progression via tryptophan depletion and aryl hydrocarbon receptor activation." (PMID 38732512, 2024). "Beyond these arguments, the limited expression of IDO2 in normal tissues reinforces its potential as a selective target for therapeutic intervention against cancer." (PMID 39594642, 2024). "IDO2 expression in human normal cells is poor, but significant in various cancers, with two prevalent SNPs." (PMID 39594642, 2024). "An increased expression of both IDO1 and IDO2 has been observed in various types of cancer including an AhR-mediated expression of IDO2 in the human mammary epithelial cell line MCF10A." (PMID 37408267, 2023). "With respect to cancer cell functions, small interfering RNA (siRNA)-mediated knockdown of IDO2 inhibited cancer cell proliferation, induced cell cycle arrest in G1 and apoptosis, and reduced cell migration of B16-BL6 melanoma cells in vitro." (PMID 37876966, 2023). "A recent study found the expression of IDO1 and IDO2 in many cancer types, including breast, colon, and endometrial cancers." (PMID 37408267, 2023). "As immune regulatory enzymes, IDO1 and IDO2 have been found to be important targets of AhR to mediate immunosuppression and promote the growth of cancer cells." (PMID 37408267, 2023). "Over expression of IDO2 and its wide range of effects in cancer also justifies targeting this isoform." (PMID 36286592, 2022). "IDO2 is expressed in fewer cancers, mainly those also expressing IDO1, though additionally in colon, non-small-cell, pancreatic and renal cancers." (PMID 36286592, 2022). "Whereas IDO2 is expressed in a few cancers (four-to-six), both IDO1 and TDO2 show a much broader expression." (PMID 36286592, 2022). "To clarify, among the EBV-associated cancers that were studied, only EBV(+) GC was associated with both IDO2 and IDO1." (PMID 34944437, 2021). "Reduction of IDO2 expression in B16/BL6 cells inhibited cancer cell proliferation, arrest of the cell cycle in G1, increased the rate of apoptosis, and reduced cell migration." (PMID 33968089, 2021). "Among all the significant associations, CD36 expression was negatively correlated with ADORA2A and LAG3 in multiple cancer types, but positively associated with IDO1, IDO2, and KIR3DL1 in multiple cancers." (PMID 34234847, 2021). "IDO2 was significantly upregulated by IFN-γ in all six cancer cell lines (HT-29, HCT-116, SW620, DLD-1, H-1299, and A549), whereas TDO was upregulated in only A549 cells." (PMID 29685162, 2018). "In this study, we demonstrated that siRNA knockdown of IDO2 inhibited cancer cell proliferation, arrested cell cycle in G1, induced greater apoptosis, and reduced cell migration in vitro." (PMID 27058624, 2016). "The purpose of this study was to assess the impact of IDO2 gene silencing as a way to inhibit B16-BL6 cancer cells in a murine model." (PMID 27058624, 2016).
cancer (continued). "Here, for the first time, we show that knockdown of IDO2 using small interfering RNA (siRNA) inhibits cancer cell proliferation, arrests cell cycle in G1, induces greater cell apoptosis, and reduces cell migration in vitro." (PMID 27058624, 2016). "Little is known about the immune-independent functions of IDO2 relevant to its specific contributions to physiology and pathophysiology in cancer cells." (PMID 27058624, 2016). "Human primary gastric, colon and renal cell carcinomas were shown to constitutively express both IDO1 and IDO2 mRNA, whereas cancer cell lines generally required induction of IDO by interferon-gamma (IFNγ)." (PMID 26378585, 2015). "IDO2 was discovered independently by groups working in the areas of infectious disease, cancer research, and genomics." (PMID 25477879, 2014). "The role of IDO1 and IDO2 in cytotoxic T-cell responses directed against self has been reviewed recently with a perspective on regulating this response in the setting of cancer therapy." (PMID 25477879, 2014). "TDO is structurally distinct from IDO1 and IDO2 and has a unique function in cancer." (PMID 40332338, 2025). "IDO2 might be a promising target for cancer immunotherapy, but more studies are needed to understand its role in cancer progression." (PMID 40332338, 2025). "Besides the mRNA expression, several groups have recently demonstrated the presence of the IDO2 protein in surgical specimens obtained from patients affected by different types of cancer." (PMID 39594642, 2024). "IDO2 could therefore represent a key mechanism that both trophoblasts and cancer cells exploit to escape regulatory control, highlighting IDO2 as a potential target for cancer therapies aimed at disrupting these shared pathways." (PMID 39594642, 2024). "New insights suggest that IDO2 might function more as a signaling molecule, particularly in cancer contexts, and further studies could reveal its potential as a target for cancer therapy." (PMID 39594642, 2024). "However, it is possible that the effect of IFNγ on IDO2 is cell-type-specific or that higher concentrations of IFNγ are required to induce IDO2, as shown in various human cancer cell lines." (PMID 37408267, 2023). "While most of the preceding points refer to IDO1, the relative expression of IDO1 or IDO2 and that of PD-L1 or PD-L2 may have a strong influence on cancer outcome." (PMID 37296860, 2023). "Moreover, IDO1 and IDO2 have been considered to possess different abilities in anti-cancer immunity regulation." (PMID 36765782, 2023). "Indeed, IDO2 upregulation has been observed in numerous cancers, including non-small cell lung cancer, pancreatic cancer, colon cancer, gastric cancer, and renal tumors." (PMID 37408267, 2023). "The close relationship between IDO2 and CD4 + T cell infiltration in the MTC microenvironment, together with its potential prognostic implications, makes it possible for IDO2 to serve as an alternative drug target in cancer immunotherapy and as a new prognostic tool." (PMID 36319978, 2022). "It was found that the expression of IDO2 is dysregulated in a variety of cancers." (PMID 36319978, 2022). "The linkage between IDO2 expression and cancer progression is still unclear, particularly in MTC." (PMID 36319978, 2022). "Although much less studied, the IDO1 paralog IDO2 may represent a valid alternative as drug target in cancer immunotherapy." (PMID 33968089, 2021). "TDO and IDO2 also have been shown to be expressed in different cells within the cancer microenvironment and their contribution to Trp metabolism should be taken under consideration in cancer research." (PMID 33541164, 2021). "Also, IDO2 is a potential therapeutic target for diseases accompanied by immune escape, such as cancer." (PMID 34201791, 2021). "In conclusion, this study demonstrates a new non-immune-associated mechanism of IDO2 in vitro and IDO2 expression in B16-BL6 cells contributes to cancer development and progression." (PMID 27058624, 2016).
cancer (continued). "IDO2 suppression through gene silencing is a promising strategy for effective cancer therapy." (PMID 27058624, 2016). "The relatively small number of studies of IDO2 in human systems has focused on cancer and where roles in immunosuppression have been hypothesized." (PMID 25477879, 2014). "Third, the possibility that IDO2 might contribute to cancer immunosuppression in some settings where it is expressed, including brain, similar to the manner in which IDO1 has been implicated widely." (PMID 25477879, 2014). "The genetic features of cancer patients’ IDO2 might also drive their immune response." (PMID 39594642, 2024). "On one hand, IFN-γ is the most prominent inducer of the IDO1 gene; on the other hand, although several studies demonstrate that IFN-γ could induce the expression of IDO2 in human mesenchymal stem cells and some cancer cells, in human dendritic cells, the cytokine is ineffective." (PMID 39594642, 2024). "Moreover, although much less studied, IDO2 may represent an effective alternative drug target in cancer immunotherapy." (PMID 36319978, 2022). "Nevertheless, IDO2 is expressed at high levels in some human tumors and, therefore, understanding its true function/s in neoplastic contexts may propel the development of new drugs targeting enzymes of the kynurenine pathway in cancer immunotherapy." (PMID 33968089, 2021). "Therefore, we assessed if IDO2 is expressed in mouse cancer cell lines." (PMID 27058624, 2016). "Results indicated high expression of IL4I1, TDO2, NIT2, and IDO1, while IDO2, ADI1, DDC, HPD, BHMT2 exhibited low expression in most cancers." (PMID 38691253, 2024). "Moreover, targeting IDO2 together with IDO1 may open new options for cancer immunotherapy." (PMID 34201791, 2021). "For instance, it appears that the catalytic activity of IDO-2 is much lower than IDO-1, and IDO2 expression varies according to cancer type." (PMID 34944437, 2021). "However, despite the evidence of IDO2 expression in several types of malignancies, there are a limited number of studies about it in human tissues and its supposed functional role in the development and/or progression of cancer is still to be corroborated, in particular in NSCLC." (PMID 32536910, 2020). "Further research is needed to better understand the exact biological functions of IDO but also of the two other Trp-degrading enzymes IDO2 and TDO in the different compartments in cancer." (PMID 33072086, 2020). "Three enzymes, namely IDO1, indoleamine 2,3-dioxygenase 2 (IDO2), and tryptophan 2,3-dioxygenase (TDO) are found controlling this step, but only IDO1 is proved to be sensitive in many cancer types." (PMID 29651242, 2018). "The enzymes most proximal to tryptophan, which result in activation of this pathway, are IDO1, IDO2 and TDO2, and all of these enzymes have been shown to be upregulated in a variety of cancers." (PMID 27572319, 2016). "Considering that IDO2 and TDO are poorly known in the field of cancer, future studies should also consider whether blocking TDO and/or IDO2 could provide general efficacy and reduce the inherent or acquired resistance to IDO1 blockade." (PMID 39371092, 2024). "The shift towards selective inhibitors of IDO2, dual inhibitors of IDO1 and IDO2 or dual inhibitors of IDO1/2 and TDO represents a sensible trend toward a definitive assessment of the value of dioxygenase inhibition in cancer." (PMID 37296860, 2023). "In humans, the absence of IDO2 increases the risk of developing NSCLC; however, in another cancer study, lower expression of IDO2 was correlated with good prognosis." (PMID 37226257, 2023). "Increasing attention is being given to IDO2 as a potential alternative anti-cancer target when IDO1 inhibition is not effective." (PMID 37296860, 2023). "The different localization from the cytosolic one and the phosphorylation state are the first indications for the signaling function of IDO2, suggesting that the IDO2 non-enzymatic role in cancer cells is worthy of deeper understanding." (PMID 38003426, 2023).
cancer (continued). "In addition, the genes included in the low-expression group were IDO2, ADORA2A, and KIR3DL1, as they showed a lower expression level in the majority of the cancer samples." (PMID 36157232, 2022). "The KP enzymes most studied in cancer are IDO1, TDO2 and IDO2." (PMID 36286592, 2022). "Nevertheless, an important contribution of both IDO1 and IDO2 in cancer development, not mentioned before, is their involvement in NAD+ production." (PMID 34071442, 2021). "Many researchers have suggested that IDO2 could be an effective therapeutic target to treat inflammatory autoimmunity, while IDO1 has recently been under intense research focused on cancer immunotherapy." (PMID 34681715, 2021). "However, the available data indicate that the expression level of IDO1, IDO2 and TDO2 differs between cancer types and that the occurrence of each enzyme alone can be an independent prognosis factor." (PMID 34071442, 2021). "However, it was also positively correlated with multiple inhibitory checkpoint molecules (IDO1, IDO2, and KIR3DL1) in multiple cancer types." (PMID 34234847, 2021). "In this scenario, we examined IDO2 immunolabeling in 191 resected NSCLC cases, in order to better understand its expression in this cancer type and to determine its correlations with clinical-pathological parameters, other immunomodulatory molecules and patients' prognosis." (PMID 32536910, 2020). "On the other hand, it is also known that IDO2 is not expressed as a functional tryptophan-degrading enzyme, at least not in human cancer cells lines." (PMID 32536910, 2020). "We determined the expression of IDO1, IDO2, and TDO in cancer cells treated with IFN-γ." (PMID 29685162, 2018). "Subsequently, the researchers found that IDO2 may play a nonnegligible role in cancer progression by exerting many kinds of cancer-promoting effects." (PMID 36319978, 2022). "Indolamine, 2,3-dioxygenase-1 (IDO1) and IDO2 are two related, initial rate-limiting enzymes (along with the unrelated enzyme TDO) in the KP and have aroused great interest with regard to inducing cancer immunosuppression, tumor development, and metastasis and neovascularization." (PMID 34681715, 2021). "Targeting IDO2 and TDO in addition to IDO1 may open new windows for cancer immunotherapy." (PMID 30068361, 2018). "Previous studies have not reported such a remarkable effect of IDO2 on lymph node metastatic status, suggesting that IDO2 may play distinct roles based on the pathophysiologic feature or immune microenvironment of different cancers." (PMID 36319978, 2022). "Similarly to human cancer, IDO2 is not frequently expressed in mouse tumors." (PMID 33968089, 2021).
infection (11 papers, 2012 to 2024). The state of being infected such as from the introduction of a foreign agent such as serum, vaccine, antigenic substance or organism. "The difference between these studies and our current study is that we assessed IDO2 expression and activity at far later time points after infection." (PMID 37506544, 2023). "IDO1 mRNA levels in infected mice continued to increase for 3 weeks after infection, whereas IDO2 mRNA levels showed an opposite trend." (PMID 35045867, 2022). "The induction of Ido1 and Ido2 transcripts by IFNγ within OHSCs mimics the cytokine-mediated response of the brain to a peripheral infection." (PMID 27142940, 2016). "Additionally, infection led to a repression of Ido2 on the transcriptomic and proteomic level in the liver." (PMID 33045014, 2020). "However, based upon data in this report, it is quite possible that specific Ido2 transcripts will be induced by bacterial (e.g., LPS) or viral (e.g., pI:C) infection within the brain." (PMID 27142940, 2016). "IDO2 expression and activity is triggered by SARS-CoV-2-infection, but the severity of SARS-CoV-2-induced pathology appears related to the generated specific kynurenine metabolites." (PMID 37506544, 2023). "DNA microarray or next-generation sequencing data also showed that IDO2 and TDO2 are up-regulated by infection or immune activation." (PMID 34871367, 2021). "In these experiments, we did not get any visible expression of IDO2 (data not shown) during the entire length of infection, and the level of TDO was also unchanged both in uninfected and infected cells." (PMID 30770800, 2019). "However, given that NAD+-consuming enzymes could help fight infection, an alternative explanation for the up-regulation of IDO1/IDO2/TDO2 is to promote NAD+ biosynthesis." (PMID 34871367, 2021). "Mining a single cell RNA-seq (scRNA-seq) dataset (GSE123688) confirmed a significant infection-induced upregulation of Tdo2 in hepatocytes and further confirmed that Ido1 is not expressed whereas Ido2 seems to be very lowly expressed in hepatocytes and not differentially regulated." (PMID 33045014, 2020). "Interestingly, we found that after infection with Mtb, the expression level of only IDO1 significantly increased in inflammatory macrophages, whereas other tryptophan-degrading enzymes, such as IDO2 and TDO2, did not significantly change." (PMID 39438693, 2024). "There are two other tryptophan-metabolising enzymes, IDO-2 and TDO (tryptophan dioxygenase), that could drive the kynurenine pathway in the absence of IDO-1, but their role in immunity to infection is not well understood." (PMID 22649518, 2012).
adenocarcinoma (2 papers, 2020 to 2021). A common cancer characterized by the presence of malignant glandular cells. "It is worthy of note that among the adenocarcinoma subgroup, high IDO2 expression was associated with an intratumoral or mixed localization of the TILs (94 and 91% of the cases, respectively), in a statistically significant manner (p < 0.001; OR = 11.4)." (PMID 32536910, 2020). "Moreover, the fact that high IDO2 expression is associated, among adenocarcinomas, with intratumoral and mixed localization of TILs could suggest a possible role for IDO2 as an immunomodulatory molecule." (PMID 32536910, 2020). "In the adenocarcinomas group, the univariate analysis showed that the patients with higher levels of PD-L2 (p = 0.02), IDO-2 (p = 0.005) and INFγ (p = 0.01) had a shorter RFS than patients with lower levels." (PMID 33671892, 2021). "IDO2 showed a high expression when associated with a specific NSCLC histotype: in fact, in our series its high expression was found especially in adenocarcinomas (p < 0.001; OR = 4.9)." (PMID 32536910, 2020). "On the other hand, among the adenocarcinomas group it was seen that the higher the expression of IDO2, the lower the expression of PD-L1 (p = 0.035; OR = 4.0)." (PMID 32536910, 2020).
psychiatric diseases (1 paper, 2016). "Thus, the role of Ido2 in inflammation-dependent psychiatric diseases is unknown." (PMID 27142940, 2016).
renal disease (1 paper, 2019). "There is some evidence that IDO1 and/or IDO2 activity can affect complement activation in different diseases, however the exact mechanism remains unknown and no study has specifically investigated the role of IDO on complement in renal disease." (PMID 31555267, 2019).